CD44 (CD44 molecule (IN blood group))
Diseases named in the same sentence as CD44 in open-access papers (continued):
Sharing a sentence is not in itself a finding about the gene and the disease.
tumor (continued). "Initial studies identified CD133 as a putative marker for GSCs; however, recent studies indicate that CD133 negative stem cells also harbor tumor initiating capacity and additional markers such as SSEA-1/CD-15, L1CAM, A2B5, CD90 and CD44 have been proposed." (PMID 26307681, 2015). "The rate of tumor growth was significantly less in CD24-positive (p = 0.0003), and CD44-positive (p = 0.0003) tumors compared to the negative populations." (PMID 26449187, 2015). "In comparison with ESA+CD44−CD24+lin− non-CSC tumor cells, 14 miRNAs were up-regulated and 13 were down-regulated in the ESA+CD44+CD24−lin− CSC cells." (PMID 26497855, 2015). "Whereas the xenografts with CD44-depleted MDA-MB-231 cells did not form tumors, the largest tumor burdens were detected in MDA-MB-231 cells with CD44ICD overexpression." (PMID 25909162, 2015). "Remarkably, however, the CD44+α2β1+ LAPC9 cells, unlike CD44+α2β1+ Du145 cells, demonstrated > 900 fold enrichment in tumor-initiating capacity compared to the double-negative cells." (PMID 26246472, 2015). "Since Hh signaling plays a critical role in mammary stem cell maintenance within the mammary epithelium, it is not surprising that mammary CD44+/CD24−/lowLin− CSCs express increased mRNA transcript levels of PTCH1, GLI1 and GLI2 compared to bulk tumour cells." (PMID 26270676, 2015). "RC cells had the following immunophenotype: positive for CD10, CD19, CD20, CD22, CD38, CD43, CD44, and CD79b and negative for CD3, CD4, CD5, CD8, CD11c, CD14, CD30, CD56, and CD200, which was identical to the primary tumor cells." (PMID 26515759, 2015). "We found that 14 miRNAs were up-regulated and 13 were down-regulated in the ESA+CD44+CD24−lineage− CSCs, related to ESA+CD44−CD24+lineage− non-CSC tumor cells." (PMID 26497855, 2015). "CD44 expression is not the only independent prognosticator for STS; in fact, previous studies have shown that the resection margin and tumor size represent independent prognostic indicators." (PMID 24491153, 2014). "The sorted CD44+CD24− CSC, CD44+CD24+, and unsorted tumor cells, but not CD44− cells, formed typical mammospheres in the presence of leukemia inhibitory factor in vitro." (PMID 25301732, 2014). "In contrast to PSA-NCAM or CD44, NCAM+ALDH1+ cells reduced the number of p-WT Xn cells required to initiate tumours in mice to as few as 200, while NCAM+ALDH1− cells lacked this ability." (PMID 23239665, 2013). "A trend toward higher levels of expression of ALCAM, CD24, and CD44, but not PROM1, was observed in CXs derived from D61540 when compared with their parental tumor." (PMID 24278200, 2013). "The mRNA levels for several critical components of the pathway (BIRC5, CD44, FZD7, c-MET, MMP7, c-MYC, NOTCH1, PPARD, and VEGF) were significantly increased (DASL signal intensity) in TN tumor samples as compared to non-TN tumor samples." (PMID 24143235, 2013). "Dynamic and reciprocal interactions involving cell adhesion molecules (e.g., integrins, CD44), ECM non-cellular components (i.e., TSP-1, FN), and soluble cytokines occur between tumor epithelial cells and tumor microenvironment stromal cells." (PMID 24348463, 2013). "Unlike CD44 and CD133, the identification of tumor cells that express high levels of ALDH requires the use of the non-immunologic enzymatic ALDEFLUORTM Kit and FACS." (PMID 22876238, 2012). "Results were also mixed in the H596 model, with a significant decrease in the proportion of CD44+ cells, an increase in CD133+ cells and no significant change in CD117+ tumor cells." (PMID 23115623, 2012). "Although ADAM17 is able to cleave L1 and CD44, it seems that ADAM10 and not ADAM17 is a major sheddase for these molecules and is responsible for their constitutive shedding also from tumor cells." (PMID 23251384, 2012). "We have previously found that recombinant CD44 hyaluronan binding domain (CD44HABD) and its non-HA-binding mutant inhibited tumor xenograft growth, angiogenesis, and endothelial cell proliferation." (PMID 22216242, 2011).
tumor (continued). "Because CSCs are expected to represent a small fraction of the tumour cells, using CD90, CD44 or CD105 in combination with Aldefluor would not be likely to result in sufficient enrichment of CSCs." (PMID 22612877, 2011). "Further analysis of the primary tumor by RT-PCR revealed the expression of the pluripotency markers POU5F1, NANOG and SOX2 in CD44+ but not CD44− subpopulations." (PMID 21124918, 2010). "CD44−/CD133− cells did not form tumor, whereas 1×104 CD44+/CD133+ cells formed tumor in 4 out of 4 mice, 1×103 CD44+/CD133+ cells formed tumor in 2 out of 4 mice, and no tumor formed with 1×102 cells." (PMID 19714243, 2009). "In these entities CD44+/CD24−, CD44+/EpCAMhigh, or CD44+/Bmi-1high cells but not CD44− cells were able to recapitulate human tumours in vivo in immunocompromised mouse recipients." (PMID 18852874, 2008). "Although the percentage of proliferating tumor cells (i.e. Ki-67+) did not appear altered, there was noticeably more cell death (i.e. TUNEL+ cells) and ESA+CD44+ cells were more frequent in tumors from CPA-treated mice." (PMID 18560594, 2008). "In contrast, PTN+ cells did not exhibited significant spatial patterns, suggesting that, in addition to CD44+ tumor cells, other cells may contribute to PTN signaling activation and regulation in a manner independent of tumor edge CAFs and neutrophils." (PMID 40069574, 2025). "CD133-positive and CD44-positive cells (unlike CD133-positive CD44-negative cells) exhibit stem-cell-like features in HCC cells and tumor xenograft models, such as widespread proliferation, self-renewal ability, high tumors, chemoresistance, and the expression of genes linked to stem cells." (PMID 40647654, 2025). "We also attempted CD44 knockdown in LLC cells; however, as previously reported, these cells did not form tumours effectively and could not be used in the experiment." (PMID 39848206, 2025). "While surface markers such as CD44, CD133, aldehyde dehydrogenase 1 (ALDH1), and epithelial cell adhesion molecule (EpCAM) have been widely used to identify CSCs across various tumour types, they are not unique to CSCs and are often expressed in normal progenitor or differentiated cells as well." (PMID 41321388, 2025). "Notably, in contrast to tumour tissue, we did not detect any GZMB+ cells among activated CD44+CD8+ T cells in tdLNs or spleen of tumour-bearing mice." (PMID 38658748, 2024). "Furthermore, the CS-mediated NP penetration was only seen in WT but not CD44−/− CT26 tumorsphere, suggesting a role of CS/CD44-mediated transcytosis in tumor penetration." (PMID 38177179, 2024). "Similarly, CD44 and CD133 expression in GBC tissues were correlated with tumor size and lymphatic metastasis but not with age or sex." (PMID 39138521, 2024). "Heatmap analysis of gene expression in adherent cells and stem‐like tumor spheres revealed a negative correlation between YY2 and stem‐related factors, including CD44, SOX9, SALL2, KLF15, OCT4 (also known as POU class 5 homeobox 1 or POU5F1), MYC, ASCL1, and POU3F2." (PMID 37300334, 2023). "However, it primarily focused on the evolution of tumor cells and did not study the change of TAMs affected by the activation of SPP1/CD44 signaling." (PMID 37194413, 2023). "Moreover, CD44-redirected CAR-Ts showed no signs of toxicities toward healthy tissues and significantly inhibited tumor growth in CD44-positive HCC xenograft mice." (PMID 36261831, 2022). "As expected, PC tumor cells showed enhanced expression of CD44 (p = 0.0007) and CD133 (p = 0.0224) together with significantly reduced proliferation rate (p<0.0001) as compared to primary tumor cells, whereas the upregulation ofc-Myc was not significant (p = 0.2826)." (PMID 35844581, 2022).
tumor (continued). "As we reported recently, unsorted parental Caco-2 cells comprised three representative subpopulations (non-tumor-initiating CD44−CD133- cells, non-tumor-initiating CD44−CD133+ cells, and tumor-initiating CD44+CD133+ cells); however, a CD44+CD133− Caco-2 fraction was barely detectable." (PMID 35433695, 2022). "In addition, several studies demonstrated that CD133+CD44+ cells exhibited much higher invasion and migratory capacities in vitro than a non-CCSC subset and drove tumor metastasis formation in vivo." (PMID 33819194, 2021). "Interestingly, both the solid tumor mass and the 11/12 identified disseminated tumor cells (DTCs and DTC cluster) in CSF were negative for both CD74 and CD44 expression." (PMID 34209696, 2021). "Tumor growth was clearly observed in control BALB/c nu/nu mice inoculated with the CD44− SK-LMS-1 subclone (normal human LMS subclone cell) fraction; however, no reduction in tumor growth was observed in BALB/c nu/nu mice inoculated with the CD44+ SK-LMS-1 subclone (human LMS stem-like cells)." (PMID 34563053, 2021). "Notably, the proportion of extensively differentiating CD45.1+ cells (>7 division, CD44+ CD62L−) increased in the lymph node and spleen, irrespective of tumor presence." (PMID 34493727, 2021). "In addition, considering that ALDEFLUOR cannot represent all tumor-initiating cells in HNC, the lack of SOD2 and resistance data in terms of the other selecting methods with CD44 or CD133 biomarkers is also a concern." (PMID 34681918, 2021). "In HCC cells and tumor xenograft models, CD133+CD44+ cells (but not CD133+CD44-) display stem cell properties, including extensive proliferation, self-renewal capacity, tumorigenic potential, resistance to chemotherapy, and expression of stem cell-associated genes." (PMID 34884878, 2021). "To understand why the Treg alteration in Prdm1fl/flFoxp3YFP-Cre mice was selectively induced in the tumor but not in the periphery, we performed RNA-seq analysis of splenic and TIL CD44+ Treg cells from WT compared to Prdm1fl/flFoxp3YFP-Cre mice in our B16-OVA/NP-OVA model." (PMID 34798898, 2021). "In the tumor cells, GFAP and CD44 expression were not recovered under SS or TMZ treatments." (PMID 34638987, 2021). "For example, one study identified two tumour initiating cell subsets within the BCSC population and demonstrated active Notch1 signalling in the more proliferative, invasive and metastatic subpopulation (CD44+/CD24low) but not the other (CD44+/CD24–)." (PMID 34295896, 2021). "However, despite both STAT3 and CD44 acting as pivotal regulators of tumor angiogenesis, there is currently no direct evidence of functional crosstalk between STAT3 and CD44 during angiogenesis promotion." (PMID 33335857, 2020). "Likewise, flow-cytometric analysis also suggested an increased percentage of CD4−CD8−CD25+CD44+Ikaros+ cells and a downregulation in CD4−CD8−CD25+CD44+Notch1+ cells within the thymus of tumor-bearing vs. control mice (Figure 4D1)." (PMID 32582141, 2020). "Furthermore, holoclones showed high expression of CD44, while CD24 was not expressed in these clones, thus representing the well‐described tumor‐initiating CD24−/CD44high population." (PMID 31834633, 2020). "Notably, despite the large number of tumor cells in the negative cell population, the tumor formation rate and efficiency of 1 × 103 purified CD133+CD44+ cells were higher than those of 5 × 107 CD133−CD44− cells." (PMID 32729895, 2020). "However, in this study the number of innate immune cells did not change significantly after CD44-targeted NIR-PIT for MOC2-luc tumor, thus we concluded that T-cell-mediated adoptive immunity mainly contributed to the anti-tumor immunity." (PMID 33322807, 2020). "Besides, DT induced deletion of Tfr cells did not influence tumor infiltrating Treg cells as well as effector CD4 T and CD8 T cells, evidenced by comparable number of Treg cells, Foxp3–CD44+CD4+ T and CD44+CD8+ T cells." (PMID 32477338, 2020).
tumor (continued). "Notably, treatment of MPM spheroids with 0.1 or 0.5 μM BI 853520 did not change the expression of the putative tumor stem cell markers SOX2, Nanog, CD44, ALDH1, c-myc, and Oct4." (PMID 30539198, 2019). "We initially examined whether eIF4A is expressed in our double positive BCSCs (ALDH+ and CD44+), ALDH− cells and the non-sorted, parental tumor population from MDA-Bone-Un cells." (PMID 31867270, 2019). "In addition, treatment with pIL-12 GET can induce a potent proliferation of memory (CD44+) CD4+ and CD8+ T cells, but not NK cells in the peripheral blood leading to induction of protection from tumor relapse and metastasis." (PMID 30544810, 2018). "The growth kinetics of MDA-MB-231 and MCF-7 xenografts suggested that TRIM28 depletion led to the inhibition of tumor growth in MDA-MB-231 cells (p = 1E-04), which have a high percentage of CD44+/CD24−/low cells, but not in MCF-7, which have a very low number of CD44+/CD24−/low cells." (PMID 27845900, 2017). "Thus, the data obtained indicate that CD44+CD24- CSCs predominate in multicellular structures and are almost absent in discrete groups of tumor cells." (PMID 28977854, 2017). "Interestingly, CD45−/CD44+ tumor cells (a mesenchymal marker) were decreased, but not CD45-/CD133+ tumor cells (hematopoietic marker) in the p65 KO tumors compared to control tumors." (PMID 29062041, 2017). "Interestingly, Rik expression was not upregulated in the splenic CD8+CD44+CD62L− T cells, suggesting that Rik was induced by the tumor microenvironment, or Rik was expressed only in tumor-specific CD8+ T cells." (PMID 28382040, 2017). "The stimuli related to PPARγ activity gave by Rosiglitazone and GW-9662, did not change the profile of tumor stem cells, translated by the absence of significant change in the percentage of this cell population, measured by the balance between CD24−/CD44+ expression." (PMID 28932171, 2017). "Presumably, the mechanisms for regulating the CD44+/CD24−/low cells are not easily altered in the non-tumorigenic population vs. cancer cells, suggesting a potentially pivotal role for this enrichment in tumor re-growth following radiation therapy." (PMID 27379202, 2016). "Other putative markers include CD44, CD24, LGR5, ALDH, and CD44v6, though not all are definitive markers that differentiate CSCs from normal adult stem cells, and inconsistent level of these markers are presented across varying stages of the tumor." (PMID 26840024, 2016). "Although pancreatic CSCs were described nearly ten years ago as CD44+/ CD24+/EpCAM+ cells or CD133+ cells, no study has determined the co-expression of all of these markers in PDAC either directly in the tumor samples or in the human PDAC cell lines derived from primary tumors." (PMID 27414409, 2016). "CD44 expression, a potential CSC marker, as determined in human BC CSC (phenotype CD44+/CD24-/low), was detected in scattered cells (score 1) in the 31% of the cases, or in limited tumor regions (score 2) in 15%, while 54% of tumors were negative." (PMID 25884842, 2015). "Only 5000 cells of CD44+/CD24-/ cells could form a tumor whereas 1 × 104 CD44-/CD24- or ESA-/CD24+ cells could not, suggesting that CD44+/CD24-and ESA+/CD24- cells have characteristics of cancer stem-like cells." (PMID 26338199, 2015). "We found that CD44- and SOX2-positive CSCs were inhibited if we inhibited mTOR signaling, which prevents the proliferation of NPC cells and reduces secondary tumor volume and weight, but OCT4-positive CSCs were not significantly affected either in vitro or in vivo." (PMID 26202311, 2015). "CD133, CD44, CD24, CDCP1, CXCR4, and CD26 have been identified as colon CSC surface antigens, but it is not well defined which are the best markers to identify a tumor stem cell due to the variability found among individuals with the same tumor type." (PMID 25685060, 2015).
tumor (continued). "Therefore, the CD44+ phenotype enriches CSCs in Du145 and LAPC9 but not in LAPC4 models whereas the ALDH+ phenotype enriches tumor-initiating cells in all 4 models except LAPC4." (PMID 26246472, 2015). "CD44 and MMP-9, however, did not co-localize on these tumor bleb structures." (PMID 24194929, 2013). "In contrast, in the Calu3 model there was a modest but significant increase in the proportion of CD44+ tumor cells, a significant decrease in the proportion of CD133+ tumor cells and no change in the proportion of CD117+ cells in tumors from chemo-treated mice." (PMID 23115623, 2012). "However, the changes of CD44+/CD24− and ALDH1+ tumour cell populations did not remain as independent prognostic factors." (PMID 21559013, 2011). "CD44+, but not CD44−, EOC cells express high levels of ALDH1, further confirming that the CD44+ EOC stem cells express the majority of identified markers for tumor initiating cells." (PMID 21904548, 2011). "However, if cellular heterogeneity exist within the CSC populations detected by the putative breast CSC markers, all the CD44+/CD24− and ALDH1+ tumour cells would not necessarily be CSCs." (PMID 21559013, 2011). "Since CD44 and CD24 were not useful markers to classify tumor cells, we wanted to determine whether additional lineage markers might be able to refine cellular differentiation states." (PMID 20964822, 2010). "Since cells capable of self-renewal reside in both side and non-side populations, we investigated whether tumor sphere cells showed any CSC features, such as the expression of stem cell markers, such as CD44, CD133 and OCT3/4." (PMID 20949018, 2010). "Since CD44 and CD24 expression alone could not be used to classify cell lines based on tumor subtype, we examined whether together these markers might be able to categorize cell lines." (PMID 20964822, 2010). "Our results indicate that overexpression of uPA, CD44 and MDR1 may involve EOC metastases and that cancer clones that escape from primary tumours do not lose these antigens." (PMID 19603017, 2009). "The expression of certain cell surface marker proteins, CD24, CD44 and CD227, was maintained during long term tissue culture-derived HBCEC, demonstrating that the extended culture conditions of the tumor tissue did not affect the expression of these adhesion molecules in the HBCEC." (PMID 19751512, 2009). "No change in uPA, CD44 and MDR1 expression was observed during the metastatic process, whereas others have observed a downregulation of CD44 during tumour progression in mice and in human ascitic tumour cells." (PMID 19603017, 2009). "Examination of the injection sites where CD44+/CD24+/ESA+ and CD44+/CD24-//ESA- cells were unable to form tumors revealed viable cells and Matrigel at the site of injection (data not shown), confirming that lack of tumor growth from these cells was not due to clearing or cell death." (PMID 18366788, 2008). "These cells, known as cancer stem cells (CSC) or tumor initiating cells, possibly originate from non-malignant stem cells or progenitor cells, with which they share several characteristics, including the expression of stem cell markers such as SOX2, NANOG, CD133, and CD44." (PMID 38303021, 2024). "However, in CD24−/CD44+‐breast CSCs xenotransplanted group treated with a low dose of doxorubicin and the potent EGFR inhibitor/compound 1e, normal morphology of mammary gland with subcutaneous fat was observed with no tumor mass." (PMID 38522013, 2024). "We first established that the promoter methylation of CD44, CD24, CD147, and CD133 was absent in normal oral mucosal tissues (n = 45), indicating that the methylation of these genes may represent an abnormal event in tumor cells." (PMID 36498950, 2022).